IL6 (interleukin 6)
Diseases named in the same sentence as IL6 in open-access papers (continued):
Sharing a sentence is not in itself a finding about the gene and the disease.
bladder cancer (continued). "In addition, using preclinical models of murine bladder cancer, we demonstrated that repeated intraperitoneal injections of DAB-1 (150 μM) inhibited tumor growth by 90% and stopped the formation of pulmonary metastasis, likely by inhibiting the TNFα/NFκB and IL6/STAT3 signaling pathways." (PMID 40807456, 2025). "Level of Pb, Cr, Hg and Cd, oxidative stress markers, and gene expression of Bcl-2, Bax, IL-6, AKT, and P38 genes were detected in cancer and non-cancerous tissues obtained from bladder cancer patients." (PMID 38072891, 2024). "In summary, we provide a novel mechanism and experimental evidence showing how the interaction between HMGN5 and Hsp27 affects bladder cancer cell invasion and EMT with or without IL-6." (PMID 32315283, 2020).
fibrosis (137 papers, 2011 to 2026). the formation of excess fibrous connective tissue in an organ or tissue in a reparative or reactive process. "High levels of IL-6 are frequently observed in numerous chronic inflammatory conditions associated with fibrosis." (PMID 41019090, 2025). "NAFLD when accompanied by fibrosis is strongly associated with systemic inflammation and elevation of hepatic as well as plasma IL-6 expression." (PMID 36968490, 2023). "This study indicates the therapeutic potential of IL-6 suppression on diabetic cardiomyopathy disease associated with fibrosis." (PMID 26972749, 2016). "Important canonical pathways linked to the top network were hepatic cholestasis, hepatic fibrosis/hepatic stellate cell activation, hepatic fibrosis signaling pathway, Il-6 signaling, B cell receptor signaling, estrogen-mediated S-phase entry, and aryl hydrocarbon receptor signaling." (PMID 38068980, 2023). "Fibrosis in SSc is caused by chronically activated myofibroblasts, and constant activation of fibroblasts is enhanced by interleukin 6 (IL-6), platelet-derived growth factor (PDGF), and transforming growth factor-beta (TGF-β), released by the immune and vascular systems." (PMID 36142646, 2022). "Functional characterization of PSMB8-AS1 in monocytes demonstrated that this lncRNA is involved in the secretion of IL-6 and TNFα, two pivotal pro-inflammatory cytokines altered in the circulation of SSc patients and associated with fibrosis and disease severity." (PMID 33922041, 2021). "The immune response is also implicated, pro-inflammatory diets activate the immune system, increasing cytokine production such as TNF-α and IL-6, which further aggravate liver damage and fibrosi." (PMID 40242166, 2025). "Fibrosis in the renal tissue has been related with the increase of pro-inflammatory cytokines, especially IL-6." (PMID 38198460, 2024). "In this manuscript, we explored the interaction between IL-6 and E2 using primary dermal fibroblasts from healthy donors, patients with dcSSc, and human dermal tissue in a skin organ culture model of fibrosis." (PMID 39000334, 2024). "Inflammatory cytokine levels (e.g., IL-6, IL-8, IL-10, TNF-α, and IFN-γ) in the synovial fluid are not only increased, but also correlate with IPFP fibrosis and have been associated with poorer clinical outcomes (e.g., Lysholm score)." (PMID 38549837, 2024). "We postulate that sterile inflammation, including the release of TNFα, IL-1β, IL-18 and IL-6, leads to changes in the endothelial-epithelial barrier and induces chronic fibrosis." (PMID 36993804, 2023). "In relation to hepatic fibrosis and hepatocarcinogenesis, the expression of hepatic inflammatory cytokines (i.e., Tnf-α, Ccl2, and Il-6) was elevated in STAM mice, compared with DIO mice." (PMID 37852976, 2023). "Our results also show that IL-6-induced Smad activation was mediated by TGF-β1 in our rat fibrosis model." (PMID 36631456, 2023). "Fibrosis regression occurred despite high expression of the canonical pro-fibrogenic cytokine Tgfb1 and, in some cases, the pro-inflammatory cytokines Il6 and Tnf, which have frequently been shown to diminish in the resolution phase of disease." (PMID 35169835, 2022). "Expression of TGFβ1, IL-11 and IL-6, mediators involved in cardiovascular fibrosis and inflammation, were increased in hearts from TRPM7-deficient mice and aldosterone-salt treated WT mice." (PMID 35882956, 2022). "This signaling interplay between Snail and IL-6 has been proposed in myofibroblast trans-differentiation during oral submucosal fibrosis, a premalignant disorder of the oral cavity." (PMID 35268073, 2022). "Higher Interleukin-6 (IL-6) increased (p = 0.0321) and lower Matrix Metalloproteinase-9 (MMP-9) serum levels (p = 0.0031) were associated with higher fibrosis as measured by Fibroscan® in multivariable regression analysis." (PMID 34813621, 2021).
fibrosis (continued). "Using an in vivo mouse model of fibrosis, we found two distinct mechanisms by which blocking IL-6, CD47 and PD-L1 reversed fibrosis, by increasing phagocytosis of profibrotic fibroblasts and by eliminating suppressive effects on adaptive immunity." (PMID 32493933, 2020). "We also measured the expression of M1 macrophage-related inflammatory factors including IFN-γ, TNF-α, and IL-6 in liver tissue, which simultaneously increased in the fibrosis group but obviously decreased in the fibrosis+MSC group." (PMID 30635047, 2019). "Renal subcapsular injection of hyper‐IL‐6 1 week after induction of nephropathy resulted in a dramatic dose‐dependent prevention of fibrosis 3 months later (using 100 ng hyper‐IL‐6 per injected kidney, but not 10 ng)." (PMID 28297566, 2017). "Overall, we have shown that the gp130 cytokines, OSM and IL-6, potentiate bleomycin-induced lung injury and fibrosis." (PMID 29038604, 2017). "mKG significantly decreased pulmonary alveolitis, fibrosis scores, and interleukin-6 (IL-6), interleukin-17 (IL-17), transforming growth factor-β (TGF-β) and hydroxyproline (HYP) levels in lung tissue of mice compared with BLM treatment." (PMID 26891294, 2016). "Treatment with IL-6 reportedly reduces carbon tetrachloride (CCl4)-induced acute and chronic liver injury and fibrosis." (PMID 27046197, 2016). "More relevant to our study, IL-6 was reported to be essential to TGF-β expression during cardiac fibrosis induced by AngII." (PMID 26121471, 2015). "We have demonstrated that IL-6 administration can significantly enhance the ability of MSCs to repair liver after CCl4 induced fibrosis." (PMID 23531302, 2013). "Visceral WAT was independently associated with hepatic inflammation and fibrosis in NAFLD subjects and serum IL-6 levels, which correlated with visceral fat, independently predicting an increase in hepatic inflammation." (PMID 23690838, 2013). "We show that IL-6 circulates in plasma at concentrations 58 times higher in individuals with advanced fibrosis than age, sex, and nearest-neighbor matched controls and 221 times higher in individuals with bile duct cancer than controls." (PMID 22629477, 2012). "For patients with predispositions to inflammatory responses, sustained elevation of IL‐6 may lead to dermal fibrosis and pathological remodeling, potentially resulting in clinical manifestations such as hypertrophic scarring or cutaneous sclerosis." (PMID 41482677, 2026). "Conversely, we investigated whether depleting IL-6 at the early stage could reduce IPFP fibrosis during OA progression." (PMID 40664639, 2025). "Furthermore, the laminectomy group shows the highest mean expression of IL6 and TGFβ-1 in laminectomy rats than in the control group and other treated groups due to epidural fibrosis formation, which agrees with the prior studies." (PMID 40804422, 2025). "TGF-β/Smad signaling pathway and cytokine IL-6 are crucial in SSc fibrosis." (PMID 39086645, 2024). "Therefore, our data suggest E2 produced through IL-6-induced aromatase activity actively contributes to dermal fibrosis by signaling through ERα to activate downstream pro-fibrotic mediators." (PMID 39000334, 2024). "A lung-specific IL6 over-expressing transgenic mouse strain showed elevated right ventricular (RV) systolic pressure as well as increased wet and dry tissue weights and tissue fibrosis in both lungs and RVs compared to age-matched wild-type littermates." (PMID 38650935, 2024). "This anti-inflammatory effect of MSCs can be a tool to oppose the IL-6 together with other pro-inflammatory mediators and thus attenuate the vigorous inflammatory response that might end up with fibrosis and pulmonary failure." (PMID 35379329, 2022). "Moreover, the present study observed a correlation between levels of IL-6 in patients and fibrosis and liver enzymes." (PMID 34221262, 2021).
fibrosis (continued). "It is possible that our findings simply reflect the increasing CV risk patients with more advanced fibrosis, rather than IL-6 playing a causative role in NAFLD pathogenesis." (PMID 34813621, 2021). "Similarly, in our studies, we have shown that IL-6 and IL-10 were increased in patients with fibrosis, together with STAT4 and STAT6." (PMID 30205811, 2018). "To investigate how OSM and IL-6 overexpression led to the increased fibrogenic response in bleomycin-induced fibrosis, we assessed pro-fibrotic and inflammatory mediators in the broncheoalveolar fluid (BALF) at day 7 after the administration of bleomycin and the adenovectors." (PMID 29038604, 2017). "Regarding IL-6, the current results revealed that a significant decrease in its expression in MSCs treated groups compared with the fibrosis group and the estrogen treated fibrosis group." (PMID 28883083, 2017). "Interestingly, in MF, irrespective of patients being at diagnosis or not, there was a positive correlation between the plasma levels of CRT and BM fibrosis (p = 0.038; r = 0.39), splenomegaly (p = 0.0089; r = 0.47), and circulating IL-6 (p = 0.028; r = 0.42)." (PMID 27672242, 2016). "Overall this work has uncovered a distinctive molecular fingerprint for scarring trachoma fibroblasts, and identified IL-6- as a potential contributor to the chronic conjunctival fibrosis, mediating reciprocal pro-fibrotic/pro-inflammatory interactions between macrophages and fibroblasts." (PMID 27321784, 2016). "To evaluate whether passive or active immunization against IL-6 influences the outcome of bleomycin-induced fibrosis by regulating leukocyte infiltration, we quantified the number of leukocytes in lesional skin." (PMID 25059342, 2014). "Fibrosis might be mediated by increased atrial expression of IL-6 and decreased atrial expression of MMP-2 with the subsequent decline in collagen-degradation." (PMID 24775918, 2014). "Therefore, combination of IL-6 and soluble factors released by MSCs can result in significantly improved hepatocyte survival against CCl4 induced fibrosis than any other treatment modality." (PMID 23531302, 2013). "Collectively, these results demonstrate that genetic removal of IL-6 in Ada-/- mice leads to attenuated pulmonary inflammation, fibrosis and air-space destruction, further implicating IL-6 signaling in mediating aspects of adenosine driven chronic lung disease." (PMID 21799929, 2011). "Because pro-inflammatory cytokines such as IL-6 and TNF-α promote hepatic stellate cell activation and extracellular matrix deposition, cytokine dysregulation has been consistently associated with increased liver stiffness and higher non-invasive fibrosis scores in MASLD." (PMID 41470883, 2025). "In addition, intravenously administered MSCs abolished the reduction in serum TGF-β1 and the increase in IL-6 in both the serum and the BALF caused by BLM treatment, which causally ameliorated BLM-induced pulmonary inflammation and fibrosis more effectively than the administration of S-MSCs." (PMID 34530920, 2021). "In addition, intraperitoneal IL-6 administration to rats increased AF susceptibility, independent of fibrosis." (PMID 34975847, 2021). "In addition, we identified cytokine IL-6 at the core of progredient fibrosis in fibrotic lung." (PMID 32493933, 2020). "Anthropometric data, lipid profile, glycemic markers, cytokines (IL-6, IL-10, TNF-α), liver stiffness, and non-invasive fibrosis indices were compared across groups using standard statistical testing." (PMID 41470883, 2025). "To further investigate the impact of AS/LIG/AS_LIG@PPGC NPs on pulmonary inflammation and fibrosis in IPF, we collected mouse BALF on Days 8 and 22 and measured the levels of IL-1β, IL-6, TNF-α, and TGF-β1 using ELISA." (PMID 38166847, 2024). "As the differentiation of Th17 cells from naïve T cells requires TGF-β, IL-6, IL-1β, and IL-23, the mRNA expression of these cytokines was investigated in lung tissues of BLM-induced fibrosis." (PMID 36674533, 2023).
fibrosis (continued). "The classic pro-inflammatory cytokines IL-6, IL-1β, and TNF-α have the effect of promoting fibrosis, which has been observed in fibrosis models of lung, heart, kidney." (PMID 37305520, 2023). "B1R blockade with BI 113823 inhibited the accumulation of macrophages and neutrophils in both CCl4 and BDL fibrosis livers, and reduced the expression of inflammatory mediators, B1Rs, COX-2, IL-1β, IL-6, MCP-1, MCP-3 and TIMP-1 in liver tissue." (PMID 36514072, 2022). "The serum TNF-α and IL-6 levels in the NAFLD group decreased after drug intervention, while in the GXZY-NASH and GXZY-fibrosis groups, SOD levels increased, MDA expression decreased, and the oxidative stress response was inhibited." (PMID 34887931, 2021). "The only exception was IL-6, whose concentration was significantly higher in F4 NAFLD patients compared to other fibrosis groups." (PMID 34943103, 2021). "Phenotypical cytokines of Fibrosis (TGF-β), vascular (PDGF) and inflammation (IL-6) were used to activate fibroblasts." (PMID 33057073, 2020). "Consistent with the literature, we found that the expression levels of IL-6, TNF-α and TGF-β1, triggering the activation of HSCs, were decreased significantly in the liver tissues of the IDO1–/– fibrosis mice." (PMID 28465467, 2017). "The subsets of monocytes from individuals with different degrees of periportal fibrosis were evaluated regarding the expression of the profibrotic markers such as IL-4Rα and TGF-β and proinflammatory cytokines such as IL-6 and TNF-α." (PMID 24757288, 2014). "Pretreatment of fibrotic liver with IL-6 improves hepatic microenvironment and primes it for MSC transplantation leading to enhanced reduction of liver injury after fibrosis." (PMID 23531302, 2013). "BLM administration increase lung concentrations of IL-1β (69.16 ± 2.69 vs. 27.36 ± 1.37, p < 0.005, t-test), IL-6 (104.7 ± 13.45 vs. 17.466, p < 0.02, t-test), and TNF-α (500.09 ± 42.19 vs. 58.84 ± 4.51, p < 0.05, t-test) observed in BLM-induced fibrosis group, compared to controls." (PMID 35326173, 2022). "Melatonin supplementation, however, reduced cardiac fibrosis and significantly decreased the expression of IL-1α and IL-6 in WT and NLRP3−/− mice, with non-significant decline of TNFα." (PMID 34439517, 2021). "IL-6 was increased by 1.4-fold (p<0.01) in advanced fibrosis patients compared to patients with no fibrosis, and increased by 1.1-fold (p<0.01) compared to mild fibrosis patients." (PMID 31291245, 2019). "Serum IL-6 was increased in patients with advanced fibrosis (2.71 pg/mL; 1.26 pg/mL; 1.39 pg/mL p<0.01) compared to patients with mild or no fibrosis respectively." (PMID 31291245, 2019). "The expression levels of IL-1β, IL-6, IL-17, TNF-α, TGF-β, and α-SMA (as a myofibroblast marker) were all decreased by anakinra treatment, which suggested anti-inflammatory and antifibrotic effects of the IL-1Ra in this BLM-induced fibrosis model." (PMID 30042768, 2018). "Furthermore, IL-17a and the mRNA expression levels of IL-6, TNF-α and TGF-β1 were decreased in the liver tissues of the IDO1–/– fibrosis mice compared with the WT fibrosis mice." (PMID 28465467, 2017). "Even absence of IL-6–the single Th1 cytokine upregulated in the hearts of SR-uPA+/0 mice preceding fibrosis–did not attenuate uPA-induced cardiac fibrosis or macrophage accumulation." (PMID 23536772, 2013). "Fibrosis is marked by an increase in the inflammatory response, tissue destruction, and the release of numerous inflammatory cytokines, including TGF-β1, tumor necrosis factor-alpha (TNF-α), monocyte chemoattractant protein (MCP-1), Interleukin-6 (IL-6), and IL-8." (PMID 36835428, 2023). "Increased levels in our study participants without fibrosis could suggest that IL-6 modulates S. mansoni related immune responses that could otherwise be harmful to the host." (PMID 29610679, 2018). "We also found elevated levels of IL-6 and TNF-α in the fibrosis groups (F2–F4), but these results were not significant." (PMID 39272729, 2024).
fibrosis (continued). "Higher levels of pro-inflammatory cytokines IFNγ, IL-6, IL-8 and TNFα were found in MASLD with fibrosis patients compared with MASLD without fibrosis." (PMID 38235661, 2024). "In contrast to the IL-6 and VCAM-1 results, CRP, TNFα, MCP-1, MIP-1β, and eotaxin levels did not change with fibrosis severity." (PMID 31291245, 2019). "Consequently, positive correlations were found between higher serum IL-6 concentrations and disease duration, European Scleroderma Study Group activity score, HRCT-ground glass score, and HRCT-fibrosis score, while negative correlations were described for DLCO% and 6 min walk distance." (PMID 37833885, 2023).